CTNNA1 (catenin alpha 1)
Diseases named in the same sentence as CTNNA1 in open-access papers (continued):
Sharing a sentence is not in itself a finding about the gene and the disease.
cancer (40 papers, 2012 to 2026). A tumor composed of atypical neoplastic, often pleomorphic cells that invade other tissues. "Microarray analysis showed that pycnogenol induced changes in the expression of various pathway genes in cancer cells, including the downregulation of CTNNA1, which is associated with increased survival of synovial sarcoma cells." (PMID 36741258, 2023). "Our findings indicate that a broader panel of cancer predisposition genes, beyond CDH1 and CTNNA1, should be included in gene panels to investigate germline variants in patients with GC." (PMID 40446793, 2025). "A total number of 649 CMTM7 binding proteins were identified, among which, CTNNA1 ranked at the leading and was selected as a cancer-related target gene." (PMID 36829181, 2023). "Mechanistically, CTNNA1 deletion has been shown to lead to an abnormal localization of E-cadherin and apoptosis resistance, resulting in cancer cells with invasive and anti-apoptotic properties." (PMID 36741258, 2023). "Genetic testing for CDH1 GPVs, and soon to include CTNNA1 GPVs, is available for affected individuals who meet the set clinical criteria whereby at least one cancer is histologically confirmed." (PMID 37258796, 2023). "Loss of LSD1 reduces the level of CTNNA1 and other cell adhesion molecules, suggesting that CTNNA1 also plays a role in the cancer suppressive function of LSD1." (PMID 36741258, 2023). "(c) Images show the effect of modulating cancer cell-cell adhesion via Crispr KO of CTNNA1 in cancer cells (green) in both organotypic and spheroid assays including fibroblasts (magenta)." (PMID 36892272, 2023). "In contrast, H413 with HC and a strong cancer signature showed a reduction of cell junctional genes except for CTNNA1 and NF2." (PMID 35000271, 2022). "Through the IPA search, CTNNA1 and CTNNB1 were related to cancer, among which CTNNB1 was a diagnostic marker for many kinds of cancer." (PMID 35268705, 2022). "It is experimentally confirmed that altered expression of CTNNA1 is correlated with dysfunction in E-cadherin mediated cell adhesion in cancer cells and also grants metastatic abilities." (PMID 33639650, 2021). "Further, several genes at central nodes in the sub-network have cell-cell and cell-matrix adhesion functions and were described in numerous human cancer entities: CTNNA1, NCAM1, and GFRA1." (PMID 27172797, 2016). "In conclusion, our results show that, in addition to CDH1 and CTNNA1 testing in families fulfilling the HDGC criteria, multi-organ cancer predisposition genes should be included in gene panels used for investigating germline variants in patients with diffuse and non-diffuse GC." (PMID 40446793, 2025). "In cancer, MATR3 was identified as one of the genes deleted from the chromosome 5 of human BLBC (primary, metastasized, and xenografted in immune-deficient mice) along with CTNNA1, LRRTM2, and SNORA74A." (PMID 32977861, 2020). "Accumulating evidences have assessed the expression levels of CTNNA1 mRNA in a variety of cancers." (PMID 27487124, 2016). "No putative pathogenic mutations in other cancer predisposition genes among which CTNNA1 and MAP3K6 were detected." (PMID 26700889, 2016). "Notably, interference of CDH1, also an inhibitor of cancer, may be involved in the cancer inhibitory effect of CTNNA1." (PMID 36741258, 2023). "(d) Images show the effect of combinatorial modulation of matrix proteolysis and cancer cell-cell adhesion via Crispr KO of CTNNA1 and/or MMP14 and/or MMP14 over-expression in cancer cells (green) in both spheroid assays including fibroblasts (magenta)." (PMID 36892272, 2023). "(b) Phase contrast images show the growth of cancer cell colonies with the indicated manipulations of MMP14 and CTNNA1 after 8 days surrounded by matrix." (PMID 36892272, 2023).
cancer (continued). "(b) Images show the effect of combinatorial modulation of matrix proteolysis and cancer cell-cell adhesion via Crispr KO of CTNNA1 and/or MMP14 and/or MMP14 over-expression in cancer cells (green) in both organotypic assays including fibroblasts (magenta)." (PMID 36892272, 2023). "All the down-regulated genes, in this Panel 3 showed their significant up-regulation in most of many types of cancers (TGM2, CSNK1A1, CTNNA1, NAMPT/Visfatin, TNFRSF1A, ETS1, SRC-1, FN1, APLP2, DMBT1/SAG, AIB1, AZIN1)." (PMID 23122428, 2012). "We anticipate two potential applications of our findings: first, HDGC-like patients who test negative for CDH1 and CTNNA1 pathogenic variants, who by HDGC definition only have diffuse tumours, should be offered a broader cancer panel." (PMID 40446793, 2025). "In fact, the IGCLC guidelines are very clear about not considering the intestinal type for CDH1/CTNNA1 testing, as this cancer type is not part of the syndrome, but they provide no guidance as regards to mixed GC." (PMID 37686589, 2023). "In addition, CTNNA1 can promote the metabolism of β-catenin by stabilizing APC, thereby inhibiting the Wnt pathway and suppressing cancer development." (PMID 36741258, 2023). "This suggests that, independently of the cancer setting (hereditary vs diffuse), or histological type (DGC vs IGC), GC developing in this CTNNA1 variant germline carrier presents a nonspecific combination of somatic events." (PMID 33724653, 2021). "INTS6P1 (integrator complex subunit 6 pseudogene) and INTS6 (integrator complex subunit 6) functioned as ceRNAs through miR-17-5p, whilst CTNNAP1 (catenin alpha 1 pseudogene) and CTNNA1 (catenin alpha 1) competed for miR-141, leading to cancer regression in HCC and CRC, respectively." (PMID 29702599, 2018). "In addition, family members of a CDH1 or CTNNA1 PV index patient, sought genetic and medical counseling, independent of personal cancer history, and were included in this study in case they were diagnosed with the same PV." (PMID 33322525, 2020). "We used GO and KEGG analysis to analyze many cancer-related genes, including QKI, CTNNA1, GSK-3b, and RGS12, which had not been previously identified in HCC." (PMID 35068348, 2022).
infection (4 papers, 2013 to 2025). The state of being infected such as from the introduction of a foreign agent such as serum, vaccine, antigenic substance or organism. "As infection continues, at 90DPI, Angiomotin like-1 (component of tight junctions) and other adherens junction proteins such as cadherin 11, 23, catenin alpha 1 and FAK also displayed significantly decreased expression." (PMID 23593167, 2013). "Lastly, there was a strong enrichment in factors involved in MAPK signalling (p value = 2.64E-19), including cell adhesion molecule CTNNA1, displayed in our network to interact with SARS-CoV-2 Orf7b protein and to be phosphorylated in response to infection." (PMID 39026801, 2024). "Although the changes in ITGA3 and CTNNA1 were not large enough to be deemed significant in this dataset, their slight elevation might contribute to subtle modifications in cell-cell contacts during infection." (PMID 40630640, 2025).
retinopathies (2 papers, 2024 to 2025). "CTNNA1 variants have been associated with retinopathies (MIM116805) but not with oCCDDs." (PMID 38585811, 2024). "Clinically, CTNNA1 should be considered in butterfly-shaped pigment dystrophy and without ellipsoid band thickening typical of PRPH2 retinopathy." (PMID 40455352, 2025).
hematological malignancies (1 paper, 2023). "Many hematological malignancies showed histone hypermethylation (H3K27me3) at the promoter of CTNNA1." (PMID 36741258, 2023).
CTNNA1 also shares sentences with these, for which no sentence is quoted: lobular breast cancer (3 papers); adenocarcinoma (1); bacterial infection (1); brain tumors (1); cardiovascular diseases (1); cholangiocarcinoma (1); cleft lip (1); Crohn disease (1); diabetic nephropathy (1); gastritis (1); genetic disorders (1); goblet cell adenocarcinomas (1); hepatic cancer (1); hepatitis B (1); hepatitis C (1); hepatocellular carcinoma (1); in situ breast carcinoma (1); invasive carcinoma (1); laryngeal carcinoma (1); Leber congenital amaurosis (1); Macular dystrophy (1); macular oedema (1); Macular Pattern Dystrophy (1); mucinous adenocarcinoma of the appendix (1); myelofibrosis (1); oropharyngeal squamous cell carcinomas (1); osteosarcoma (1); platelet disorders (1); polyposis (1); prostate carcinoma (1).
A further 5 diseases each share a sentence with CTNNA1 in 1 paper.